RNU4-40P (RNA, U4 small nuclear 40, pseudogene)
Gene: Small nuclear RNA gene on chromosome 20 (35,887,659 to 35,887,801, forward strand). Ensembl gene ENSG00000201221.
Homologues: Orthologues: chimpanzee U4 (99% identical). Paralogues in human: RNU4-11P (65% identical), RNU4-21P (65% identical), RNU4-36P (64% identical), RNU4-46P (64% identical), RNU4-15P (58% identical), RNU4-51P (57% identical), RNU4-43P (57% identical), RNU4-81P (57% identical), RNU4-49P (56% identical), RNU4-90P (56% identical), RNU4-91P (56% identical), RNU4-24P (55% identical), and 80 more.